MMP1 (matrix metallopeptidase 1)
Diseases named in the same sentence as MMP1 in open-access papers (continued):
Sharing a sentence is not in itself a finding about the gene and the disease.
tumor (continued). "Immunostaining studies indicate that more than 20% of UM tumor cells demonstrated medium MMP-1, -9, and -19 expression while over 70% demonstrated membrane-type 1-MMP expression." (PMID 35457074, 2022). "Both mRNA and protein abundance of MMP1 were highly increased in HNSCC as compared to its non-tumor counterparts." (PMID 36105241, 2022). "MMP1 overexpression positively correlated with advanced tumor size, cervical node metastasis, and advanced pathological grade and lower patients' survival." (PMID 36105241, 2022). "Our study demonstrated increased PPP metabolism promotes development of acidosis-adapted PDAC cells via AMPK/YAP/MMP1 axis, enriching the mechanism by which acidic environment promotes tumor progression." (PMID 35414794, 2022). "We compared MMP1 expression levels between tumor and normal tissues in all cancer types of TCGA via TIMER2.0." (PMID 35948625, 2022). "In this study, transcriptome data of PDTC/ATC and PTC from the Gene Expression Omnibus and The Cancer Genome Atlas databases were utilized to perform an integrated analysis of MMP1 as a potential regulator of tumor progression and dedifferentiation in PTC." (PMID 36479070, 2022). "Here, by immunohistochemistry and western blotting analysis, we demonstrated overexpression of MMP-8/-13 along with a down-regulation of MMP-1, associated with a decrease in TIMP-3 levels in tumor compared with normal skin samples." (PMID 36713871, 2022). "When co-cultured, both tumor cells and fibroblasts upregulated MMP1, while MMP1 inhibitors/silencing restored the response to cetuximab, further supporting the importance of proper matrix stiffness for the optimal response to molecular therapies." (PMID 36324182, 2022). "The MCF-7/tamR/shMMP1 cells expressing low MMP1 levels exhibited dramatically retarded tumor growth by 79% at week 8 compared to the control cells (n = 5, p < 0.05)." (PMID 35267540, 2022). "Taken together, our findings showed that WNT7B and MMP1 are involved in oral inflammation and tumor progression." (PMID 35850748, 2022). "The xenografted MCF-7/tamR cells that stably expressed short hairpin RNA (shRNA) against MMP1 exhibited retarded tumor growth compared to that in cells expressing the control shRNA, which was further suppressed by tam." (PMID 35267540, 2022). "MMP-13 and MMP-1 also played a significant role in tumor progression of eyelid BCC in a clinical study, as immunoreaction positivity was identified in most patients." (PMID 35572966, 2022). "Dysregulation of MMP transcription would promote tumor metastasis, because of its role in extracellular matrix degradation in tumor invation 59), Studies showed that MMP1 was one of the proteins that's overexpressed in various cancer)." (PMID 35444805, 2022). "We found that CAFs infiltration positively correlated with MMP1 expression in 31 tumor types, and after three algorithms validation, CAFs was significantly related to MMP1 expression in 18 tumor types." (PMID 36727076, 2022). "Previous studies have suggested that ETV4 plays a role in affecting tumor cell migration and invasion through a colony-forming assay by regulating MMP1." (PMID 35121725, 2022). "Among these, MMP1 plays a major role in tumor invasion, neoangiogenesis, metastasis, and the proinflammatory process." (PMID 33921173, 2021). "MMP1 and BMP2 are known to modulate cell activity and the tumor microenvironment, as well as being factors associated with OSCC relapse." (PMID 34445087, 2021). "We were able to show that ACh drives tumor cell invasion and migration, at least in part via an overexpression of MMP-1." (PMID 34203220, 2021). "As MMP-1 and VEGF have been clearly linked to tumor invasion and metastasis, the level of both was monitored in cell culture media under hypoxia and/or serum starvation conditions." (PMID 33445709, 2021). "A newly identified mechanism of MMP1 in tumor promotion is through activation of oncogenic signaling pathway downstream of PAR1 cleavage." (PMID 34753916, 2021).
tumor (continued). "As we developed in the S2 Text, the MMP1 activity modifies the porosity of the medium, facilitating the spread and, therefore, the transport and progression of the tumor mass." (PMID 33513131, 2021). "In general, though, MMP1, MMP10 and PTHLH were mainly associated with poor prognosis, indicating a tumor promoting role in most cancers." (PMID 34301206, 2021). "After MMP1 release into the extracellular space, their flux is limited in the areas surrounding the tumor mass, generating a sharp front ahead of the tumor." (PMID 33513131, 2021). "For example, in tumorgenesis of colon cancer, they trigger the phenotypic conversion of progenitor smooth muscle cells into matrix metalloproteinases 1 (MMP1) secreting tumor-promoting cells." (PMID 33802346, 2021). "Consistent with increased tumor invasion, we also observed intensive MMP1 activation, a protein essential for basement membrane degradation and epithelial–mesenchymal transition (EMT), in both primary tumor and invasive leading edges." (PMID 33919765, 2021). "To characterize NMUR2-positive CRC samples, we analysed the level of CDH1 (E-cadherin), a functional marker of cancer cell differentiation, and MMP1, a mediator of primary tumour invasion, in groups with various NMUR2 expression levels." (PMID 34493299, 2021). "MMP1 was found to be upregulated in all three cell lines when co-cultured with CAFs compared to tumor cells cultured alone in spheroids." (PMID 34283070, 2021). "Enhanced MMP1 expression in invasive versus intramucosal CRC suggests increased expression of MMP1 in the earlier stages of tumor invasion, a similar pattern to that for increased M3R expression." (PMID 33450835, 2021). "Uptake of these EVs by stromal cells lead to their conversion to tumor promoting cells, activation of signaling pathways, induction of MMP1 expression and increased tumor cell invasion." (PMID 33995103, 2021). "Intriguingly, C4-2B cell cycle was significantly reduced after treatment, confirming the potential role of MMP-1/PAR-1 pathway in tumor growth." (PMID 34966687, 2021). "MMP1 dynamics are characterized by an increased protein concentration along the TM region, indicating an enhanced tumor proteolytic activity, and by a steep profile ahead in the direction of tumor migration." (PMID 33513131, 2021). "Generally, increased expression of MMP-1, MMP-2, MMP-3, MMP-7, MMP-9, MMP-13, and MMP-14 are associated with cancer advancement, which relates to poor cell differentiation, tumor invasion, distant metastasis, and poor prognosis." (PMID 33892690, 2021). "A statistical analysis of these data found that Mmp1 level of cephalic complex or ventral nerve cord (VNC) was remarkably reduced in foi RNAi tumour flies, showing 52% and 40% decrease, respectively, compared to RafGOFscrib−/− flies." (PMID 34564691, 2021). "Altogether, these data more definitively establish MMP1 as a signaling molecule that can elicit direct and diverse cellular effects to accelerate tumor progression, and further expand the repertoire of MMP functions." (PMID 34753916, 2021). "Our study reveals significantly reduced TWEAK in tumor samples, which is negatively correlated in tumor tissues with MMP1 and MMP3." (PMID 33846436, 2021). "Bone resorption promoted by tumor cells (secretion of PTHrP, IL-11, CTGF, CXCR4, MMP-1) releases factors that stimulate tumor cells themselves, establishing a positive feedback mechanism (vicious cycle) that results in the spread of bone metastatic disease." (PMID 34212564, 2021). "They revealed that the expression of MMP-1 in tumor cells was five times higher in morpheaform and recurrent BCC than in superficial, cystic or micronodular BCC." (PMID 34204372, 2021). "It is interesting to point out that MMP-1 is responsible for collagen degradation within the primary tumor site, thus playing a crucial role in local invasion, while its activity does not affect the distant dissemination of tumor cells." (PMID 34199373, 2021).
tumor (continued). "Experimentally, to analyze the protein distribution in the tumor we quantified the MMP1 signal in the inner GB mass and at the GB front." (PMID 33513131, 2021). "MMP1, MMP3, and MMP1 can break down extracellular matrices and potentially contribute to tumor invasion." (PMID 33606788, 2021). "Then, JN collects information about the cell response to the gradient of soluble and insoluble components of the tumor microenvironment, precisely gradients of MMP1 P(t, x) and active integrins A(t, x)." (PMID 33513131, 2021). "MMP-1 is expressed in various cells, including fibroblasts, hepatocytes, and tumor cells, and the level of expression is consistently high even without evident stimulation." (PMID 34502094, 2021). "Among the down-regulated genes, GLI1 and some other tumor progression related genes were discovered, for example, MMP1, MMP9, NFKB2, TGFA, and EGFR." (PMID 33637972, 2021). "Acetylcholine-induced p38, ERK1/2 and Akt signaling, and MMP-1 mRNA expression were decreased by darifenacin, as well as matrigel invasion of tumor cells." (PMID 34203220, 2021). "Recently, another wasting model in Drosophila, relates the FB remodelling and muscle detachment to the tumor-secreted matrix metalloproteinase 1 (Mmp1)." (PMID 34993199, 2021). "The activated Mmp1 expression in RafGOFscrib−/− flies was significantly suppressed when foi was knocked down in the tumour cells." (PMID 34564691, 2021). "We have shown earlier that CAFs increase resistance to cetuximab treatment (a monoclonal antibody against EGFR; Erbitux®, Merck KGaA) and increase the MMP1 expression of HNSCC cells during co-culturing compared with tumor cells grown alone in a 2D model." (PMID 34283070, 2021). "Mechanistic studies indicated that MMP1/PAR1 axis exerts its tumor promotion by activating MAPK/Erk pathway." (PMID 34753916, 2021). "The major MMPs associated with tumour angiogenesis are MMP‐2, MMP‐9 and MMP‐14, followed by MMP‐1 and MMP‐7." (PMID 31957271, 2020). "The median concentration of salivary MMP-1 in patients with T0-1 (tumor diameter < 2 cm), T2 (2–4 cm), T3 (>4 cm), and T4 (tumor infiltrated to nearby tissue) was 429.6, 1975.9, 4620.1, and 2294.5 pg/mL, respectively." (PMID 32823758, 2020). "Genes related to tumor progression, including matrix metallopeptidase 1 or MMP1, S100 calcium binding protein A2 or S100A2, tetraspanin 8 or TSPAN8, and insulin like growth factor binding protein 7 or IGFBP7 were upregulated in GSM3516665-subgroup 2." (PMID 33170151, 2020). "Proteases such as ADAM9, ADAM10, TSLI and MMP-1, -2, -9, -11, and -12 have been found in colon primary tumor but not in metastasis, suggesting their role in migration of primary tumor cells." (PMID 32984031, 2020). "The expression levels of MMP-1, 2, 3, 9, 10, and 13 declined in the tumor tissues isolated from mice treated with chrysin-NPs when compared with the control mice." (PMID 33042020, 2020). "Because CD147 was demonstrated to induce MMP-1 expression in co-cultured tumor cells and fibroblast cells, it was considered an MMP inducer." (PMID 31926558, 2020). "Western blot analysis of tumour spheres further showed that the expression of EMT‐associated proteins including N‐cadherin, vimentin, MMP‐9 and MMP‐1 was up‐regulated, whereas E‐cadherin expression was down‐regulated." (PMID 32396269, 2020). "EEVs derived from gastrointestinal stromal tumor patients show enhanced MMP1 secretion by smooth muscle cells compared to healthy donors and induce tumor cell invasion." (PMID 33126572, 2020). "It has been reported that MMP1 enhanced tumor cell invasiveness by increasing vascular endothelial growth factor (VEGF) and bone morphogenetic protein 2/4." (PMID 32703314, 2020). "These include pro-MMP-1, -2, -3, -8, -9, and -13 and degrade type-I collagen, and all contribute to degradation of the extracellular matrix and promote tumor cell invasion and metastasis." (PMID 32948029, 2020).
tumor (continued). "Here, we showed that loss of PER2 enhanced tumor invasion by activating transcriptional genes of EMT, including TWIST1/2, ZEB1/2, and MMP1, suggesting a wide-range influence of PER2 on EMT process." (PMID 32185221, 2020). "MMP1 expression increases in malignant tumor cells, which is helpful for tumor cell invasion and metastasis." (PMID 32636440, 2020). "The NSCLC-with-IPF tumor tissue displayed a distinctly stronger expression of MMP1 compared with the other tissue samples, and the staining was mainly localized to the glandular epithelium and extracellular stroma." (PMID 33046043, 2020). "Tumor sections from ITLN-treated mice also showed significantly lower MMP1 expression levels than did sections from control buffer-treated mice." (PMID 32669559, 2020). "MMP-3 as one of the most important MMPs has been correlated to metastases by promoting epithelial–mesenchymal transition (EMT), it is also capable of activating MMP-1, which increases the capacity of the tumor cells to invade." (PMID 33167431, 2020). "This MMP1 staining furthermore reveals that an arborescence of tracheas grows inside the tumours from the tracheas that are normally situated at the surface of the accessory glands." (PMID 32385236, 2020). "It binds to type I collagen and induces expression of matrix metalloproteinase 1 (MMP1) to promote tumor invasion, bone resorption, and angiogenesis." (PMID 33634031, 2020). "In this context, none of the micro-RNA deregulated in brain metastatic tumors were tested for their ability to regulate MMP-1, a key player in the transmigration of tumor cells trough the brain endothelium." (PMID 33002044, 2020). "Several studies have reported that UVB-induced ROS causes skin photoaging via the promotion of the activity of MMP-1 in human keratinocytes and dermal fibroblasts, and accordingly, it would be desirable to identify an effective antioxidant that could be used to prevent skin aging." (PMID 30669248, 2019). "In these xenograft mice, [Pt(O,O′-acac)(γ-acac)(DMS)] also displayed potent antiangiogenic activity though the inhibition of vascular endothelial growth factor (VEGF) and matrix metalloproteinase-1 (MMP-1) expression in tumor tissues." (PMID 30845773, 2019). "IL-1β was previously shown to promote tumour cell invasion and metastasis by modulating the expression of matrix metalloproteinases in cancer cells, specifically MMP1, MMP3, and MMP1045." (PMID 31558756, 2019). "That is why the expression of MMP-1 in tumor tissue is considered as unfavorable factor for PC prognosis." (PMID 31582998, 2019). "In RCCs, overexpression of MMP-1, MMP-2, and MMP-9 is linked to tumour stage, histological grade, progression, invasion of microvasculature, and distant metastasis." (PMID 31771219, 2019). "As a member of the MMP family, MMP1 encodes an enzyme that breaks down the ECM, and promotes tumor cell division and metastasis." (PMID 30967896, 2019). "On the contrary, in tumor cells with active RAS, apoptosis is blocked and JNK signaling acts as a tumor promoter transcribing genes involved in growth and invasion such as MMP1." (PMID 30881374, 2019). "MMP-1, or collagenase 1, is involved in the destruction of the connective tissue component of the tumor stroma and creates conditions for the development of PC metastases." (PMID 31582998, 2019). "The elevation of tumor invasion is supported by our sequencing results that demonstrated TNFα up-regulates invasion-related genes of MMP1, MMP9, MMP14, LAMB3, and FGF2 which all have been previously reported to increase OSCC cancer invasion." (PMID 30018735, 2018). "Especially, activation of RAS/MAPK signaling increases the expression of MMP-1 but represses PER expression in tumor cell lines." (PMID 29570674, 2018).
tumor (continued). "In the present study, we further demonstrated that MMP‐1 secreted by the highly tumor‐tropic MSCs cleaved the IGF‐2/IGFBP2 complex that resulted in the release of free IGF‐2, which facilitated MSC migration toward tumor cells via the IGF‐2 signaling axis." (PMID 29321953, 2018). "In this study, we examined the functional roles of IGF‐2 and MMP‐1 in mediating the tumor tropism of MSCs." (PMID 29321953, 2018). "Taken together, these results showed that the MMP‐1 secreted by highly tumor‐tropic MSCs cleaved IGF‐2/IGFBP2 complex." (PMID 29321953, 2018). "Apelin stimulation also induced expression of APJ receptor and matrix metalloproteinase-1 (MMP-1), matrix metalloproteinase-9 (MMP-9), IL-1, and IL-6, which are associated with tumor invasion and metastasis." (PMID 29875677, 2018). "The expression and activity of MMP‐1 were determined in two representative MSCs with high and low tumor‐tropic properties." (PMID 29321953, 2018). "Mmp1 staining revealed that its upregulation in ph tumours is prevented by blocking JNK signaling either with bskDN or upon knocking down egr or grnd." (PMID 29357360, 2018). "It is commonly activated in tumours and is required for invasion and malignant phenotypes, mediated for instance by its target Mmp1 or in cooperation with other transcription factors." (PMID 29357360, 2018). "Matrix metalloproteinase 1 (MMP-1) expression in tumour-invaded peritoneum was more intense in the peripheral invasion zone between the tumour and normal peritoneal tissue, indicating an active role of MMP-1." (PMID 29623449, 2018). "This was associated with a decrease in invasion-associated genes (e.g., Fibronectin, VCAM1, Thrombospondin, MMP1) and an increase in CDH1/E-cadherin, previously associated with decreased tumor aggression." (PMID 29735912, 2018). "In fact, PAR1 senses and responds to multiple proteases generated in the tumor microenvironment including thrombin, plasmin and matrix metalloproteinase-1 (MMP-1)." (PMID 29954076, 2018). "In our data, we identified a switch from MMP1, 3 and 13 in primary tumours to MMP1, 9 and 12 in metastases, as well as a significant upregulation of CXCL12/CXCR4." (PMID 29743718, 2018). "The massive upregulation of MMP1 in Nact/lgl-IR tumor was drastically suppressed, when bsk-DN (a dominant negative allele of Drosophila JNK gene, basket) was expressed in the background." (PMID 29661224, 2018). "TTP is a regulator of MMP-1, -2, -9, uPA/uPAR and other factors which play important roles in tumor metastasis." (PMID 29728635, 2018). "The lncRNA BANCR promotes EC cell replication and tumor invasion, by regulating Matrix MetalloProteinase-1 (MMP1) and MMP2, and via extracellular signal-regulated kinase-1 (ERK)–MAPK signaling pathways." (PMID 29596364, 2018). "The TNCB cell line MDA-MB231 over-expresses the pro-metastatic matrix metalloprotease 1 (MMP1), and inhibition of MMP1 attenuates tumor intravasation." (PMID 29593542, 2018). "Our finding that MMP‐1/PAR‐1 signaling is necessary for MSC tumor tropism is in accordance with the study of Ponte AL and colleagues where IGF is one of the most potent chemotactic factors in stimulating bone marrow‐derived MSCs." (PMID 29321953, 2018). "PAR1-dependent tumor growth was MMP1-mediated because treatment with MMP-1 Inh resulted in 82% inhibition of tumor growth." (PMID 30065181, 2018). "We thus tested for possible association between MMP expression and caspase activation during ICM, using an antibody against MMP1, one of two Drosophila MMPs, involved in basement membrane degradation and tumor invasion." (PMID 30022065, 2018). "In the present study, we examined the functional roles of IGFs and MMP‐1 in mediating MSC tumor tropism." (PMID 29321953, 2018). "In our case, Nact/lgl-IR tumor resulted in severe apoptosis along with strong overgrowth and MMP1 expression." (PMID 29661224, 2018).